CRP (C-reactive protein)
Diseases named in the same sentence as CRP in open-access papers (continued):
Sharing a sentence is not in itself a finding about the gene and the disease.
hemorrhagic stroke (38 papers, 2013 to 2026). A stroke caused by a bleed on the brain. "CRP levels rise in response to systemic inflammation and are linked to both ischemic and hemorrhagic strokes." (PMID 39258059, 2024). "Genetic studies have shown that the significantly reduced expression of haplotype H5 in the CRP genotype is closely associated with hemorrhagic stroke." (PMID 37077571, 2023). "CRP elevation displays negative prognostic implications for many conditions, while elevations in CRP as a consequence of the major acute-phase response following ischemic or hemorrhagic stroke are associated with death and vascular complications." (PMID 29951057, 2018). "A case-control study involving 236 hemorrhagic stroke patients in a community of Han Chinese population revealed that SNP rs3091244 (−286C/T/A) of the CRP gene was significantly associated with elevated CRP levels in male patients." (PMID 30254628, 2018). "Immune system activation is another key mechanism, as prolonged inflammation leads to elevated levels of inflammatory markers, such as CRP, which promote vascular inflammation and compromise blood-brain barrier integrity, increasing the risk of both ischemic and hemorrhagic strokes." (PMID 40686813, 2025). "Likewise, genetic variants in CRP, rs3093068, rs1130864, rs1205, have been identified in correlation with CRP concentrations and previously in ischemic and haemorrhagic stroke (+ 1059G > C, + 1444C > T, − 757A > G, − 717A > G, − 286C > T > A and + 2147C > T)." (PMID 37833739, 2023). "This would suggest that CRP and Hcy-lowering therapy could reduce the risk and/or severity of hemorrhagic stroke." (PMID 30613458, 2018). "This study underscores the significant role of HDL, CRP, and serum ferritin levels in differentiating between ischemic and hemorrhagic stroke patients." (PMID 39258059, 2024). "This study highlights the significant role of HDL, CRP, and serum ferritin levels in distinguishing between ischemic and hemorrhagic stroke patients." (PMID 39258059, 2024). "In contrast, hemorrhagic stroke patients have a lower mean CRP level of 22.80 mg/L with a broader SD of 10.97 and a 95% CI of 19.75 to 25.85 mg/L." (PMID 39258059, 2024). "For cases of hemorrhagic stroke, polymorphisms in collagen genes, TLR4 and CD14 and even the gene that gives rise to C-reactive protein were identified." (PMID 38478535, 2024). "The study aims to analyze and compare the levels of HDL, CRP, and serum ferritin in patients diagnosed with ischemic and hemorrhagic strokes." (PMID 39258059, 2024). "This study aims to investigate the role of high-density lipoprotein (HDL), C-reactive protein (CRP), and serum ferritin levels in people who have had ischemic and hemorrhagic strokes in order to identify possible biomarkers for diagnosis and treatment." (PMID 39258059, 2024). "Biomarkers such as tumor necrosis factor alpha (TNFα), C-reactive protein (CRP), homocysteine (Hcy), and vascular endothelial growth factor (VEGF) have previously been associated with differential findings in ischemic and hemorrhagic stroke." (PMID 33585095, 2021). "Elevated CRP is clearly recognized in the major acute-phase response following ischemic or hemorrhagic stroke, and it is related to the development of vascular complications." (PMID 34447386, 2021). "The predictive value of MCP-1 instead of CRP was also reported in studies devoted to biomarkers of community-acquired pneumonia, hemorrhagic stroke and cardiovascular disease (CVD) mortality." (PMID 33918634, 2021). "From both experimental and clinical data, increasing evidence suggest that elevated CRP concentrations are associated with an increased risk of CVD, T2DM, AD, hemorrhagic stroke, PD, and AMD." (PMID 29951057, 2018). "Four genetic studies have been conducted hitherto, one of which has shown that haplotype ATC of CRP SNPs (rs2794521, rs3091244, and rs1205) is an independent prognostic marker for hemorrhagic stroke." (PMID 30254628, 2018).
hemorrhagic stroke (continued). "Up to 60% of patients had fever and nearly 100% of large ischemic and hemorrhagic stroke patients had pathological serum CRP values >5 mg/l." (PMID 24069356, 2013). "For instance, elevated S100B protein levels are associated with worse outcomes, while markers like D-dimer, CRP, and NSE assist in distinguishing between ischemic and hemorrhagic strokes, as well as gauging event severity, corroborating studies by Jickling and Kamtchum-Tatuene." (PMID 41173049, 2025). "Current high-sensitivity platforms fail to discriminate between CRP isoforms—an omission that may limit their relevance in hemorrhagic stroke." (PMID 40649973, 2025). "The age-adjusted incidence rates of first-ever hemorrhagic stroke according to quintiles of baseline serum CRP were 2.4, 1.1, 2.2, 1.9, and 2.7 per 1,000 person-years for men, and 1.1, 2.6, 1.0, 1.3, and 1.6 per 1,000 person-years for women with no significant trends in either sex." (PMID 30254628, 2018). "Elevated CRP levels were associated with excessive risk of ischemic but not hemorrhagic stroke." (PMID 30254628, 2018). "The main finding was the lack of any association between CRP and risk of hemorrhagic stroke." (PMID 30254628, 2018). "In conclusion, both the Pan-Immune Inflammation Value (PIV) and the C-reactive protein–albumin–lymphocyte (CALLY) index serve as robust prognostic biomarkers in both ischemic and hemorrhagic strokes by integrating inflammatory, immunological, and nutritional axes." (PMID 41602960, 2026). "Further studies into modulating CAR after the onset of hemorrhagic stroke can be studied to evaluate the utility of modifying CRP and albumin in an inpatient setting, rather than only as a preventative measure." (PMID 33585095, 2021). "However, elevated CRP and Hcy levels were associated with a non-significant trend in hemorrhage size and mortality suggesting that CRP and Hcy-lowering therapies may decrease hemorrhagic stroke risk and severity." (PMID 30613458, 2018). "However, in our cohort of patients with hemorrhagic stroke, CRP, PCT, and WBC did not prove to be reliable parameters for the diagnosis of VRI." (PMID 35547383, 2022).
Hyperbilirubinemia (38 papers, 2008 to 2026). An increased amount of bilirubin in the blood. "In addition, more severe inflammatory processes, as reflected by high CRP or hyperbilirubinemia, have been associated with a higher risk of developing IVIG-refractory disease or coronary artery aneurysms." (PMID 38264503, 2023). "Significant hyperbilirubinemia was independently associated with CRP ≥ 10mg/l (AOR 3.96, CI 1.23–12.73, p 0.021), ABO discordance (AOR 3.67, CI 1.28–10.49, p 0.015), jaundice in a previous sibling (AOR 3.565, CI 1.10–11.51, p 0.034) and time of first feed > 1 hour (AOR 2.74, CI 1.10–6.90, p 0.007)." (PMID 36407330, 2022). "A recent review of the literature found that hyperbilirubinemia is the most commonly seen abnormality, followed by elevated liver enzymes and CRP." (PMID 40656420, 2025). "TLC, C-reactive protein and hyperbilirubinemia adjuvant to clinical examination make the easy and early decision for appendectomy." (PMID 33679912, 2021). "All patients in our study demonstrated known TBRF biochemical alterations in the acute phase, including high levels of C-reactive protein, mild hypertransaminasemia, and hyperbilirubinemia." (PMID 32308194, 2020). "In our series, all patients presented with an elevated CRP level, yet abnormal liver enzymes or hyperbilirubinemia were found in less than half, which paralleled the relatively scarce occurrence of clinical subjective jaundice." (PMID 32266189, 2020). "When divided by left ventricular ejection fraction (LVEF), patients with an LVEF ≤40% had a higher prevalence of high urea, CKD stage 3 to 5, hyperbilirubinemia, deranged liver function test results, and elevated CRP and troponin‐T, than patients with a LVEF >40%." (PMID 38314569, 2024). "Over half of the patients diagnosed with NAC stage 3 disease were anemic (56.7%), the overwhelming majority were uremic (94.4%), nearly one‐third had hyperbilirubinemia (32.1%), over one‐fifth had an elevated ALP (28.2%), and nearly half had an elevated CRP." (PMID 38314569, 2024). "Due to absence of information, we were unable to assess the utility of other biochemical markers, such as C-reactive protein (CRP), hyperbilirubinemia and hyperfibrinogenemia, in predicting appendiceal perforation in our population." (PMID 37853433, 2023). "We showed that cholestasis and hyperbilirubinemia findings of HLH patients at the initial diagnosis should be considered in favor of primary HLH, and an increased level of CRP should be considered in favor of secondary HLH." (PMID 25408853, 2014). "Laboratory evaluation on admission revealed normal renal function and electrolytes at baseline; however, labs also showed hyperbilirubinemia, elevated alkaline phosphatase (Alk phos), gamma-glutamyl transferase (GGT) levels, and a high C-reactive protein (CRP) level." (PMID 40135029, 2025).
macrophage activation syndrome (38 papers, 2016 to 2025). A complication of rheumatic disease that is caused by excessive activation and uncontrolled proliferation of T lymphocytes and well-differentiated macrophages. "This hyperinflammatory immune response mimics a macrophage activation syndrome (MAS) which is characterized by high CRP, neutrophilia, and hyperferritinemia." (PMID 33850271, 2021). "In fact, signs of macrophage activation syndrome were observed in CG, such as an increase in CRP, inflammatory cytokines and the predominant presence of monocytes/macrophages in the pulmonary alveoli, observed in post-mortem analyses." (PMID 33815368, 2021). "Subjects with macrophage activation syndrome had higher serum C reactive protein (CRP), ferritin, and IL-1β levels and lower white blood cell count than those with lymphocyte depletion." (PMID 32423059, 2020). "Inflammatory markers, especially ferritin and C-reactive protein levels, are elevated and findings consistent with macrophage activation syndrome (MAS) or hemophagocytic lymphohistiocytosis (HLH) may be seen." (PMID 34360549, 2021). "Notably, this secondary burst of cytokines is associated with other hyperactive immune disorders such as hemophagocytic lymphohistiocytosis (HLH) and macrophage activation syndrome (MAS), with inflammatory markers such as C Reactive protein and ferritin becoming elevated." (PMID 32076597, 2019). "In patients with no concomitant macrophage activation syndrome, erythrocyte sedimentation rate (ESR), C reactive protein (CRP), and ferritin serum levels are generally increased during disease activity." (PMID 36619631, 2022).
mood disorder (38 papers, 2016 to 2025). A cognitive disorder a disturbance in which the person's mood is hypothesized to be the main underlying feature. "Associated with reduced levels of inflammatory markers (such as C-reactive protein), which correlates with a lower risk of neurodegenerative diseases and mood disorders." (PMID 40077754, 2025). "Elevated levels of pro-inflammatory cytokines such as IL-6, TNF-α, and C-reactive protein (CRP) are commonly observed in individuals with inflammatory depression and have been linked to increased vulnerability to mood disorders." (PMID 41162174, 2025). "Four biological parameters were selected that in earlier research were found to be associated with inflammatory events in mood disorders: IL-6, CRP, Zn, and albumin levels." (PMID 38785543, 2024). "The similarity in IL-6, Zn, CRP, and albumin levels between UD and BD during depressive episodes of similar severity suggests common underlying pathophysiological processes in mood disorders." (PMID 38785543, 2024). "Initial Kaplan–Meier methods found that the baseline TSH values, CRP levels, IL-16 levels, and anti-TG antibody levels were associated with incidence of mood changes during follow-up." (PMID 37090700, 2023). "This study is one of the first to systematically explore the associations among inflammatory, CRP and mood disorders using mitochondria-wide association study and mtDNA×CRP association analysis." (PMID 37344456, 2023). "Specifically, associations between the increased CRP and incidence and the severity of mood changes were investigated in a relatively large sample." (PMID 37090700, 2023). "In this study, OC use was associated with elevated CRP in females as demonstrated by others, and in an independent sample of subjects with mood disorders." (PMID 35821205, 2022). "The aim of this study of UK Biobank participants was to determine the magnitude of the associations between CRP, mood disorder, and cognitive function." (PMID 33517931, 2021). "In this large cohort of individuals of white British ancestry in middle to early old age, some evidence was found of associations between CRP, mood disorder, and cognitive function." (PMID 33517931, 2021). "Increased serum CRP was significantly associated with mood disorder history (Kruskal–Wallis H = 196.06, p < 0.001, η2 = 0.002) but increased polygenic risk for CRP was not (F = 0.668, p = 0.648, η2 < 0.001)." (PMID 33517931, 2021). "This study is one of the first to explore the association between CRP and mood disorder incorporating both serum CRP level and PRS-CRP." (PMID 33517931, 2021). "Suicide attempts were associated with psychotic (p < 0.001) and mood disorder (p < 0.001) diagnoses, with entering the study as screen-positive (p = 0.007), and with higher CRP (p = 0.004)." (PMID 32219505, 2020). "Another study implies that severe mood disorders are associated with alterations in circulating levels of both markers of impaired intestinal permeability, and markers of systemic inflammation such as CRP." (PMID 38540315, 2024). "Investigating these other biomarkers may better explain the association between inflammation, mood disorder, and cognitive function, as they reflect more specific inflammatory pathways rather than the general inflammatory levels which are indicated by CRP." (PMID 33517931, 2021). "The inclusion of serum and genetic CRP variables within the same study allowed us to compare the effect of current measured inflammation levels, versus genetic predisposition to inflammation, on mood disorder history and cognitive performance." (PMID 33517931, 2021). "Our finding that CRP was negatively associated with corpus callosum QA values is consistent with the hypothesis that systemic inflammation may contribute to the etiology of mood disorders." (PMID 35054436, 2021). "Finally, the study aimed to determine whether an increased serum CRP level or PRS-CRP moderated the association between a lifetime history of mood disorder and cognitive performance." (PMID 33517931, 2021).
mood disorder (continued). "Furthermore, the dysregulation of thyroid function and systemic inflammation, as evidenced by altered thyroid hormone levels and elevated concentrations of C-reactive protein, may play a contributory role in the neuroendocrine and immunological mechanisms underlying mood disorders." (PMID 40566031, 2025). "fMRI studies revealed a positive relationship between CRP levels and threat-related amygdala activity in mood disorder patients." (PMID 35558424, 2022). "It is recognized that an increase in the level of CRP and pro-inflammatory cytokines is considered to be a pathogenetic agent of mood disorders." (PMID 35956393, 2022). "Including both serum CRP and PRS-CRP within the same study would ensure the effects of current and genetic levels of CRP were accounted for when investigating the relationship between CRP, mood disorder, and cognitive function." (PMID 33517931, 2021). "The most prominent cytokines associated with mood disorders include: interleukin-1 beta (IL-1ß), interleukin-6 (IL-6), tumor necrosis factor alpha (TNF-alpha), and C-reactive protein (CRP)." (PMID 34113269, 2021). "Compared to the unadjusted model, the effect sizes increased for all serum CRP quintiles whilst they decreased for all mood disorder groups." (PMID 33517931, 2021). "Tests for interactions between serum CRP level and mood disorder, and PRS-CRP and mood disorder, were conducted in the adjusted models for each cognitive test." (PMID 33517931, 2021). "Neuroinflammation has been increasingly implicated in mood disorders, with elevated pro-inflammatory cytokines such as interleukin-6 (IL-6), tumor necrosis factor-alpha (TNF-α), and C-reactive protein (CRP) contributing to neuronal dysfunction and treatment resistance." (PMID 40969698, 2025). "Thus, nomograms were developed in the vaccine group to quantify the risk of mood changes and the risk of TSH increases by means of anti-TPO antibodies, TSH, and CRP values before vaccination." (PMID 37090700, 2023). "Second, we did not have specific experiment results regarding mtDNA × CRP associations for mood disorders, in addition, the observed mtDNA × CRP interactions in the presents study do not necessarily mean causality." (PMID 37344456, 2023). "The association between mood disorder and lower cognitive performance was small and did not appear to be moderated by CRP level." (PMID 33517931, 2021). "The association between mood disorder and worse cognitive performance was very small and did not vary by CRP level." (PMID 33517931, 2021). "More severe mood disorder categories were significantly associated with worse cognitive performance and this was not moderated by serum or genetic CRP level." (PMID 33517931, 2021). "The null hypothesis that serum CRP level was the same across all mood disorder groups was rejected (Kruskal–Wallis H statistic = 169.06, df = 5, p < 0.001, η2 = 0.002)." (PMID 33517931, 2021). "Our results suggested that increased serum CRP level was significantly associated with a history of mood disorder whereas an increased PRS-CRP was not." (PMID 33517931, 2021). "Suicidal thoughts were as common in males as in females and were significantly associated with psychotic (p < 0.001) and mood disorder (p < 0.001) diagnoses and with entering the study as screen-positive (p < 0.001) but not with CRP (p = 0.525)." (PMID 32219505, 2020). "Baseline CRP, TSH, and antibodies of thyroid peroxidase (anti-TPO) were found to predict incidence of mood changes." (PMID 37090700, 2023). "Elevated levels of CRP have also been found in patients with mood disorders having attempted suicide compared to non-suicidal individuals." (PMID 41446303, 2025). "However, recent systematic reviews and meta-analyses in mood disorders and neurodegenerative diseases emphasise both the variability and methodological challenges of using peripheral BDNF and CRP for biomarker-informed stratification." (PMID 41367212, 2025).
mood disorder (continued). "Incidence rate of mood changes was 17.3% in patients with increased CRP and 10.9% in patients without an increase." (PMID 37090700, 2023). "Specific inflammatory markers such as TNF-α, IL-1β, CRP, and TSPO may be commonly involved in the pathogenesis of both SUD and mood disorders." (PMID 35558424, 2022). "The overall absence of significant interactions between CRP measures and the mood disorder groups suggests that the relationship between mood disorder history and cognitive function did not vary substantially across different levels of CRP." (PMID 33517931, 2021). "The lack of significant association between PRS-CRP and mood disorder was perhaps unexpected although the positive correlation between serum CRP level and PRS-CRP shows there may be more to investigate regarding this relationship." (PMID 33517931, 2021). "However, there was a significant positive correlation between serum CRP level and genetic predisposition to higher CRP, which may mean that a relationship does exist between PRS-CRP and mood disorder but could not be detected with the available data in this study." (PMID 33517931, 2021).